PLSCR1 (phospholipid scramblase 1)
Diseases named in the same sentence as PLSCR1 in open-access papers (continued):
Sharing a sentence is not in itself a finding about the gene and the disease.
tumor (continued). "Thus, we collected tissue pairs of adjacent normal and tumor tissues that overexpressed PLSCR1 and examined the expression of the adaptor protein Shc, Src, and cyclin D1." (PMID 23259795, 2012). "The tumor growth may be repressed via blocking of PLSCR1-related tumorigenic signals and/or antibody dependent cell-mediated cytotoxicity." (PMID 23259795, 2012). "Consistent with this concept, PLSCR1 expression resulted in increased CSC properties by promoting transactivation of STAT1 in BLBC, implying the critical role of PLSCR1 in controlling the viability of CSCs, which are implicated in mediating tumor initiation and metastasis 39-41." (PMID 32292520, 2020). "Taken together, these results indicate that wogonoside promotes the expression of PLSCR1-associated cycle- and differentiation-associated proteins in U937 xenografts, and triggers tumor regression in NOD/SCID mice without detrimental effects on the status of normal organs." (PMID 28492556, 2017). "The anticancer microRNA miR-628-5p accelerates tumor suppression in human PDAC, probably by directly targeting the PLSCR1 and insulin receptor substrate 1 (IRS1) genes through inhibition of AKT/NF-κB signal pathways." (PMID 35422844, 2022). "To investigate PLSCR1 expression in different solid cancers and adjacent normal tissues, we analyzed immunohistochemistry tissue arrays with NP1 using 54 tumor cases from 27 types of human organs, plus 90 cases from 24 common types of normal human organs." (PMID 23259795, 2012). "By immunohistochemical analysis we identified 7 samples (22%) in which PLSCR1 expression was detectable in 10% or more of neoplastic cells and 25 cases (78%) in which it was expressed by less than 10% of tumor cells or was absent." (PMID 27248824, 2016). "In addition, recent studies have shown tumour cells have highly dysregulated PS signalling due to altered flippase activity and cellular calcium environment, suggesting that these cells might not provide an accurate reflection of PLSCR1 activity." (PMID 40835608, 2025).
cancer (13 papers, 2012 to 2025). A tumor composed of atypical neoplastic, often pleomorphic cells that invade other tissues. "In addition to its anti-viral function, PLSCR1 appears to be implicated in cancer development and cellular responses to chemotherapeutic agents." (PMID 25658875, 2015). "For instance, in myeloid cells, PLSCR1 interacts with the c-Myc target onzin, a protein that has been reported to promote cell survival and proliferation in specific cancer lineages." (PMID 35650588, 2022). "PLSCR1 can also interfere with other viruses able to promote cancer development, including the human T-lymphotropic virus type 1 (HTLV-1), a virus known to cause adult T-cell leukemia/lymphoma and neurodegenerative disorders." (PMID 35650588, 2022). "More recently, Snail, an EMT co-transcriptional repressor, has been identified to regulate PLSCR1 transcription potentially implicating a role for PLSCR1 in modulating the aggressiveness of certain cancers." (PMID 25658875, 2015). "PLSCR1 is overexpressed in various cancer cells and interference with PLSCR1 expression inhibits proliferation, invasion capacity and tumorigenesis." (PMID 24260178, 2013). "However, studies on different cancer types have revealed controversial roles of PLSCR1 and their complex regulatory mechanism leading to malignancy." (PMID 35422844, 2022). "As the cytosol turns acidic in many malignant cell types, PLSCR1 might be a key regulatory protein of cancer progression." (PMID 35422844, 2022). "Both the phosphorylation sites and the Shc and Src binding sites are located in the N-terminal domain of PLSCR1, suggesting that this peptide domain may be a potential target in cancer therapy." (PMID 23259795, 2012). "Besides promoting PS exposure, PLSCR1 may affect apoptosis through other mechanisms involved in cancer progression." (PMID 35650588, 2022). "In fact, whereas PLSCR1 interactions with cytoplasmic proteins, such as onzin, ATG12/ATG5 or AIF, may promote neoplastic cell death, its nuclear association with STAT3 or MK would rather enhance cancer cell proliferation and progression." (PMID 35650588, 2022). "On the contrary, downregulation of PLSCR1 expression, which is also seen in RAMA 37-28 cells, significantly inhibited the proliferation, adhesion, migration and invasion of cancer cells." (PMID 37239828, 2023). "Many cancer-cell invasion and migration-promoting genes such as SERPINE1, PLSCR1, ITGA2, MMP14, etc. are significantly down-regulated in the IGROV1 cells." (PMID 34949722, 2022). "PLSCR1 was enriched in the promoter region of STAT1 and enhanced STAT3 binding to the STAT1 promoter, resulting in transactivation of STAT1; STAT1 then enhanced cancer stem cell (CSC)-like properties that promoted BLBC progression." (PMID 32292520, 2020). "There exist other IRF family members which may be responsible for regulation of PLSCR1 in the cancer cell lines; certainly, there are reports that various TLRs and IRF family members are expressed differentially in certain cancer cell types." (PMID 25658875, 2015).
epithelial carcinomas (1 paper, 2015). "PLSCR1 is located proximal to the 3q26.2 amplicon, which is dysregulated in ovarian as well as other epithelial carcinomas." (PMID 25658875, 2015).
immune diseases (1 paper, 2016). "PLSCR1 is mostly highly expressed in Neutrophils, Dendritic Cells, and Macrophages.This referenceexpression pattern, together with expression patternunder disease status, may be helpful for ascertaining key immunological cell subsets for a specific immune diseases, including SLE." (PMID 27257790, 2016).
PLSCR1 also shares sentences with these, for which no sentence is quoted: acute promyelocytic leukemia (3 papers); rheumatoid arthritis (2); acne (1); AIDS (1); antiphospholipid syndrome (1); autoimmune disease (1); Autoimmunity (1); chronic hepatitis B (1); depression (1); diabetic nephropathy (1); esophageal adenocarcinoma (1); gastrointestinal tumors (1); glioblastoma multiforme (1); glioma (1); intestinal cancer (1); ischemia (1); lung adenocarcinoma (1); medullary thyroid carcinoma (1); melanoma (1); myeloma (1); pancreatic adenocarcinoma (1); rectal adenocarcinoma (1); Renal failure (1); respiratory infection (1); triple-negative breast carcinoma (1).